SESN2 (sestrin 2)
Diseases named in the same sentence as SESN2 in open-access papers (continued):
Sharing a sentence is not in itself a finding about the gene and the disease.
cardiac hypertrophy (3 papers, 2019 to 2021). "The reduction of Sesn2 expression was the main cause of cardiac hypertrophy in aged heart and may be a useful target for future drug and gene therapy treatment efforts." (PMID 32863202, 2020). "Furthermore, we show that adeno-associated virus 9 (AAV9)-Sesn2 transfection can partially reverse cardiac hypertrophy in aged wild-type (WT) mice." (PMID 32863202, 2020). "Results of HE and PSR staining showed that Sesn2 overexpression significantly alleviated cardiac hypertrophy and fibrosis in mice hearts induced by pressure overload." (PMID 34867324, 2021). "Taken together, these data exhibited that Sesn2 overexpression protected against pressure overload-induced cardiac hypertrophy." (PMID 34867324, 2021). "Sesn2 overexpression inhibited cardiac hypertrophy, since it decreased CSA in the TG + AB group compared to the WT + AB group." (PMID 34867324, 2021). "In the present study, we show that Sesn2 plays an important role in the regulation of cardiac hypertrophy." (PMID 32863202, 2020). "In the present study, pressure overload induced the expression of Sesn2; the development of cardiac hypertrophy induced further increase in Sesn2 expression, which modulated mTORC1 and inhibited 4EBP1 and S6, thus delaying myocardial hypertrophy." (PMID 32863202, 2020). "Sesn2 knockout or aging enhances pressure overload-induced cardiac hypertrophy through excessive activation of mTOR, which is the key regulator of myocardial metabolism." (PMID 32863202, 2020). "There were three important findings: 1) Pressure overload induced the expression of Sesn2, which inhibited cardiac hypertrophy by suppressing mTORC1 activity." (PMID 32863202, 2020). "Our study showed that Sesn2 prevented pressure overload-induced cardiac hypertrophy by inhibiting mTORC1 through interactions with the GATOR2 complex." (PMID 32863202, 2020). "As reported, in a phenylephrine-induced hypertrophy model, SESN2 expression was decreased in the process of cardiac hypertrophy, and SESN2 retarded the cardiomyocyte hypertrophy process by inhibiting ERK1/2 signaling." (PMID 31867002, 2019). "Thus, this study firstly demonstrated that transgenic Sesn2 overexpression negatively regulated cardiac hypertrophy and combating oxidative stress, which was dependent on AMPKα2 regulation." (PMID 34867324, 2021). "Sesn2 overexpression could mitigate pressure overload-induced cardiac hypertrophy in vivo and Ang II-induced NRCMs hypertrophy in vitro via activating AMPKα2, depressing ACC1/mTORC1 signaling, and oxidative stress, as well as restoring Nrf2/HO-1 signaling." (PMID 34867324, 2021). "In previous studies, Sesn2 has been suggested to regulate the MAPK, AKT, AMPKα, and oxidative stress-associated signaling pathways, all of which have been implicated in the regulation of pathological cardiac hypertrophy." (PMID 34867324, 2021). "The regulation of AMPK-mTORC1 signaling pathway by Sesn2 might be more potent than other anti-oxidants in depressing ROS overproduction in pathological cardiac hypertrophy." (PMID 34867324, 2021). "Strategies on regulating Sesn2 expression by genetic or pharmacologic means might be effective for preventing pathological cardiac hypertrophy and heart failure." (PMID 34867324, 2021). "Therefore, this study intends to investigate the role and mechanisms of Sesn2 in cardiac hypertrophy with Sesn2 transgenic and AMPKα2 knockout mice by establishing a pressure overload-induced cardiac hypertrophy model via aortic banding (AB) surgery." (PMID 34867324, 2021). "To verify whether the reduced levels of Sesn2 in aged hearts contributed to their intolerance to cardiac hypertrophy, we used adeno-associated virus 9 (AAV9)-Sesn2 to rescue the impaired Sesn2 level in aged WT (Aged) hearts." (PMID 32863202, 2020). "Therefore, we plan to construct Sesn2-overexpressing mice to further investigate the role of Sesn2 in cardiac hypertrophy." (PMID 32863202, 2020).
cardiac hypertrophy (continued). "In this study, we systematically investigated the role of Sesn2 in myocardial hypertrophy; the results showed that Sesn2 inhibits myocardial hypertrophy by inhibiting the mTORC1 pathway, thereby regulating protein synthesis, metabolism, autophagy, and apoptosis." (PMID 32863202, 2020). "Thus, Sesn2 rescue can partially ameliorate pressure overload-induced cardiac hypertrophy induced in aged WT mice." (PMID 32863202, 2020). "However, the effects and underlying mechanisms of Sesn2 in adult mouse cardiac hypertrophy have not been clearly illustrated." (PMID 34867324, 2021). "Our study demonstrated that Sesn2 overexpression could attenuate oxidative stress in pathological cardiac hypertrophy via increasing Nrf2/HO-1 signaling pathway and SOD activity but decreasing the production of MDA, p67, and 4-HEN and depressing NADPH activity." (PMID 34867324, 2021). "Thus, interventions through promoting Sesn2 expression might be a potential strategy for treating pathological cardiac hypertrophy and heart failure." (PMID 34867324, 2021). "However, the roles and mechanisms of Sesn2 in pressure overload-induced mouse cardiac hypertrophy have not been clearly clarified." (PMID 34867324, 2021).
colitis (3 papers, 2016 to 2022). Inflammation of the colon. "Reports have suggested that loss of sestrin 2 correlates with severe colitis due to its role in maintaining intestinal homeostasis." (PMID 33673488, 2021). "However, tumor size and burden were dramatically increased in Sesn2-/- mice, suggesting that Sestrin2 loss promoted tumor growth and progression in the colitis-associated cancer model." (PMID 26913956, 2016). "Therefore, the effect of RE pre-treatment on expression of sestrin 2 protein in DSS colitis mice was determined." (PMID 33673488, 2021). "Additionally, sestrin 2 downregulates the mTOR activity, which is a strategy for treating colitis in humans due to its role in regulating cellular stress and inflammation." (PMID 33673488, 2021). "Sesn2-/-/Sesn3-/- mice also showed a dramatic decrease in colon length when compared to WT mice, indicative of strongly exacerbated DSS-induced colitis." (PMID 26913956, 2016). "The same study also showed that sestrin 2-/- mice could not recover from dextran sodium sulfate (DSS)-induced colitis." (PMID 33673488, 2021). "However, none of Sesn2-/- mice (n=7) survived the first round of colitis induction, while WT mice were able to survive the entirety of the treatment." (PMID 26913956, 2016).
endothelial dysfunction (3 papers, 2014 to 2024). In vascular diseases, endothelial dysfunction is a systemic pathological state of the endothelium (the inner lining of blood vessels) and can be broadly defined as an imbalance between vasodilating and vasoconstricting substances produced by (or acting on) the endothelium. "The amplified oxidative stress in SESN2-deficient cells underscores its importance in maintaining redox balance, a critical factor in preventing endothelial dysfunction in diabetic conditions." (PMID 39769227, 2024). "For example, we have previously shown that SESN2 alleviates oxidative stress-induced endothelial dysfunction by upregulating antioxidant defense systems and promoting the activation of the AMPK pathway." (PMID 39769227, 2024). "This study, although offering significant insights into the function of SESN2 in endothelial dysfunction and EndMT, exhibits some limitations." (PMID 39769227, 2024). "A key finding of our study is that the absence of SESN2 has promoted EndMT, a process associated with endothelial dysfunction and vascular remodeling." (PMID 39769227, 2024). "SESN2, as a cytoprotective protein, has been shown to exert protective effects against oxidative stress, inflammation, and other pathological stimuli leading to endothelial dysfunction." (PMID 39769227, 2024). "Despite the established protective role of SESN2 in endothelial cells, the impact of its suppression on EndMT and MGO-induced endothelial dysfunction remains to be elucidated." (PMID 39769227, 2024). "Under normal conditions, expression of SESN2 is found to take place in endothelial cells; however, alterations in SESN2 expression in the process of endothelial dysfunction are not yet understood." (PMID 24838122, 2014).
ischemic encephalopathy (3 papers, 2016 to 2025). "Intranasal administration of recombinant human SESN2 (rh‐SESN2) provides neuroprotective effects in hypoxic–ischemic encephalopathy by conditioning the AMPK/mTOR pathway in rat newborns." (PMID 40032632, 2025). "In addition, in hypoxia-ischemic encephalopathy models, severe hypoxia-ischemic injury upregulated SESN2 expression in a HIF-1α-dependent manner, and SESN2 inhibited vascular endothelial growth factor formation and attenuated brain infarction or edema." (PMID 31867002, 2019). "The mechanisms Sesn2 exerts its protective effects against oxidative damage in cerebral ischemia remain unclear." (PMID 27453548, 2016). "Moreover, we demonstrated that cerebral ischemia–reperfusion injury (CIRI) promoted mTOR/HIF‐1α signaling pathway expression, which could be further enhanced via the knockdown of SESN2." (PMID 40032632, 2025).
liver cancer (3 papers, 2021 to 2025). An epithelial or non-epithelial malignant neoplasm that arises from the liver. "Notably, there have been conflicting reports regarding sestrin 2 alterations in lung and liver cancer." (PMID 34784907, 2021). "Furthermore, sestrin 2 was identified as a potential candidate gene for the diagnosis and therapy of liver cancer." (PMID 34784907, 2021). "For instance, under glucose deprivation stress in liver cancer cells, NRF2 regulates the expression of sestrin 2 (SESN2)." (PMID 38247494, 2024).
liver diseases (3 papers, 2020 to 2023). "In this review, we summarize the biological functions of SESN2 in distinct pathophysiological processes and particularly describe its association with liver diseases, aiming to promote profound understanding for the medical significance of SESN2." (PMID 36841824, 2023). "Induced SESN2 may serve as a cellular defender against multiple detrimental stimuli and contribute to the recovery of organ homeostasis from diseases, especially liver diseases." (PMID 36841824, 2023). "In addition, the findings from preclinical studies uncover the favorable outcome of SESN2 regulation in the intervention of liver damage with no obvious side effects, which suggests that SESN2 may be a promising therapeutic target for liver diseases." (PMID 36841824, 2023).
myocardial ischemia (3 papers, 2021 to 2025). A disorder of cardiac function caused by insufficient blood flow to the muscle tissue of the heart. "In contrast to Sestrin 1, Sestrin 2 is activated under hypoxic conditions induced by ischemic injury as most widely characterized by myocardial ischemia/reperfusion injury." (PMID 36252128, 2022). "Sestrin2 protein accumulates in the heart during myocardial ischemia, and the myocardial infarction area in Sesn2 knockout mice was significantly larger than that in wild-type mice when myocardial ischemia reperfusion occurred." (PMID 34803916, 2021).
ovarian carcinoma (3 papers, 2017 to 2021). A malignant neoplasm originating from the surface ovarian epithelium. "Sestrin 2 promoted ovarian cancer cell survival by suppressing the anti-tumor effects of NK-92 cells through activation of AMPK and inhibition of the mTORC1 pathway." (PMID 34784907, 2021). "In this study, using an ovarian cancer xenograft mouse model and NK-92 cell line, we identified the up-regulation of SESN2 and SESN3 in intratumoral NK-92 cells." (PMID 29163816, 2017). "SESN2 and SESN3 suppress NK-92 cell-mediated cytotoxic activity on ovarian cancer cells through the induction of AMPK and inhibition of mTORC1, pointing at its potential relevance for immunotherapy in ovarian cancer." (PMID 31205582, 2019). "The up-regulation of SESN2 and SESN3 in intratumoral NK-92 cells was also observed in another subcutaneous ovarian cancer model using SKOV3 cells." (PMID 29163816, 2017). "Taken together, our data highlights the crucial effects of SESN2 and SESN3 on NK-92 cell-mediated anti-ovarian cancer activity." (PMID 29163816, 2017). "In conclusion, our data highlights the negative effects of SESN2 and SESN3 on NK-92 cell-mediated anti-ovarian cancer activity." (PMID 29163816, 2017).
Parkinson disease (3 papers, 2018 to 2025). A progressive degenerative disorder of the central nervous system characterized by loss of dopamine producing neurons in the substantia nigra and the presence of Lewy bodies in the substantia nigra and locus coeruleus. "It has been demonstrated that SESN2 contributes to chronic inflammation associated with neurodegenerative diseases, such as Alzheimer's disease (AD) and Parkinson's disease (PD)." (PMID 31867002, 2019). "Elevation in levels of SESN2 has been found in the mid brain of Parkinson’s patients (PD) while in-vitro neuroblastoma cells showed a protective role of SESN2 against 1-methyl-4-phenylpyridinium (MPP+) induced neurotoxicity." (PMID 29330382, 2018).
pulmonary fibrosis (3 papers, 2022 to 2024). Chronic progressive interstitial lung disorder characterized by the replacement of the lung tissue by connective tissue, leading to progressive dyspnea, respiratory failure, or right heart failure. "We found that CDKN2B-AS1 inhibited the proliferation of pulmonary fibrotic cells by regulating the miR-199a-5p/SESN2 axis, and promoted the occurrence of apoptosis and activated autophagy, and finally alleviated the occurrence of pulmonary fibrosis in mice." (PMID 35291918, 2022). "To understand the mechanism by which miR-199a-5p and SESN2 are involved in pulmonary fibrosis, we investigated the behavioral transformation of TGF-β-induced cells by inhibiting miR-199a-5p and SESN2." (PMID 35291918, 2022).
sebaceous gland carcinoma (3 papers, 2019 to 2025). A cancer that involves the sebaceous gland. "The lower expression of sestrin 2 was associated with advanced tumor stage, lymphatic and vascular invasion, liver metastasis, shorter disease-free and overall survival, upper eyelid involvement in sebaceous gland carcinoma, and radiosensitization." (PMID 34784907, 2021).
Stroke (3 papers, 2010 to 2025). Sudden impairment of blood flow to a part of the brain due to occlusion or rupture of an artery to the brain. "Moreover, how increased lactate production caused by the knockdown of SESN2 affects stroke outcome needs further elucidation, which can be investigated by examining the corresponding sites of histone lactationization." (PMID 40032632, 2025). "First, at 72 h after stroke, we detected the expression of SESN2 and glycolysis‐related proteins in the peri‐ischemic region by WB." (PMID 40032632, 2025). "In an experimental model ofacute stroke, Sesn2 was shown to be highly induced upon hypoxic injury,suggesting that Sesn2 may exert its neuroprotective role during stroke." (PMID 20606249, 2010).
age (2 papers, 2016 to 2020). A temporal measurement of the time period elapsed since an identifiable point in the life cycle of an organism. "Sestrin-2 (Sesn2), a member of the stress-responsive proteins, is known to play a protective role in regulating cell growth and viability, against oxidative stress and age-related pathologies." (PMID 32240104, 2020). "Recent studies showed that Sesn2 played a pivotal role in age-dependent neurodegenerative diseases." (PMID 27453548, 2016).
atrial fibrillation (2 papers, 2022 to 2023). A disorder characterized by an electrocardiographic finding of a supraventricular arrhythmia characterized by the replacement of consistent P waves by rapid oscillations or fibrillatory waves that vary in size, shape and timing and are accompanied by an irregular ventricular response. "Collagen volume fraction was increased in patients and a positive association between SESN2 concentrations and oxidative stress in atrial fibrillation patients was found." (PMID 36902310, 2023). "SESN2 also showed a protective role against oxidative stress and atrial fibrosis in a cell model of atrial fibrillation." (PMID 36902310, 2023).
brain infarction (2 papers, 2016 to 2019). Tissue necrosis in any area of the brain, including the cerebral hemispheres, the cerebellum, and the brain stem. "Sesn2 silencing exacerbated neurological deficits, increased cerebral infarction, and increased oxidative stress and neuron damage." (PMID 27453548, 2016). "However, Sesn2 knockdown exacerbated neurologic deficits and increased cerebral infarction." (PMID 27453548, 2016).
cardiac insufficiency (2 papers, 2020 to 2021). "However, it remains unknown whether the reduction of Sesn2 expression in aged heart tissue is related to the incidence and mortality of heart failure." (PMID 32863202, 2020).
complication (2 papers, 2024 to 2025). Any disease or disorder that occurs during the course of, or because of, another disease, treatment, or procedure. "Therefore, our results imply that the loss of SESN2 may not only enhance oxidative stress but also exacerbate the inflammatory milieu within the vasculature, further promoting the progression of diabetic vascular complications." (PMID 39769227, 2024). "The downregulation of SESN2 enhances oxidative stress, inflammation, and EndMT, processes that are central to the pathogenesis of diabetic vascular complications." (PMID 39769227, 2024). "Understanding how SESN2 influences this process could provide valuable insights into the pathogenesis of diabetic-induced vascular complications." (PMID 39769227, 2024). "Our results indicate that SESN2 downregulation may contribute to the pathogenesis of diabetic vascular complications by promoting EndMT, increased oxidative stress, and inflammation." (PMID 39769227, 2024). "This study highlights SESN2 as a pivotal regulator of endothelial cell homeostasis and angiogenic activity under MGO-induced stress, indicating its potential as a therapeutic target for addressing diabetic vascular complications and improving patient outcomes." (PMID 41373553, 2025).
dilated cardiomyopathy (2 papers, 2020 to 2021). Cardiomyopathy which is characterized by dilation and contractile dysfunction of the left and right ventricles. "In this study, we demonstrated that the expression of histone demethylase JMJD3 were increased, while that of SESN2 were reduced in both human hearts with dilated cardiomyopathy and DOX-induced chronic cardiomyopathy model." (PMID 33117796, 2020). "However, inconsistent with results in DOX-induced acute cardiotoxicity, we found that the transcriptional of SESN2 was depressed in dilated cardiomyopathy from human samples or following chronic Dox stimulation." (PMID 33117796, 2020).